ACSL4 (acyl-CoA synthetase long chain family member 4)
Diseases named in the same sentence as ACSL4 in open-access papers (continued):
Sharing a sentence is not in itself a finding about the gene and the disease.
triple-negative breast carcinoma (15 papers, 2012 to 2026). An invasive breast carcinoma which is negative for expression of estrogen receptor (ER), progesterone receptor (PR), and human epidermal growth factor receptor 2 (HER2). "Ultimately, our results also highlight the value of microRNAs-449 and ACSL4 as diagnostic and prognostic biomarkers in triple-negative breast cancer." (PMID 39174500, 2024). "Acyl-CoA synthetase 4 (ACSL4) overexpression plays a causal role in the aggressiveness of triple negative breast cancer." (PMID 31311992, 2019). "Altogether, our results suggest that the microRNA-449 family might be a potential therapeutic target for the treatment of triple-negative breast cancer since it is implicated in doxorubicin response through ACSL4/ABCG2 axis regulation." (PMID 39174500, 2024). "It was reported that ACSL4 was required for the maintenance of mitochondrial membrane potential (MMP) in chemo-resistant triple-negative breast cancer (TNBC) cells." (PMID 39563427, 2024). "High expression of ACSL4 can inhibit DDP resistance in triple-negative breast cancer by promoting ferroptosis." (PMID 39039611, 2024). "In this study, we proposed that Polyphyllin III exerted a proliferation inhibitory effect on MDA-MB-231 triple-negative breast cancer cells mainly through ACSL4-mediated ferroptosis induction." (PMID 34040532, 2021). "We also demonstrated that ERα restoration in triple negative breast cancer cells downregulates ACSL4 expression." (PMID 31311992, 2019). "We have shown that knocking down ACSL4 expression in the aggressive triple negative breast cancer cell line MDA-MB-231 induces ERα expression." (PMID 26536660, 2015). "Adipocyte-derived monounsaturated fatty acids such as oleic acid suppress lipid peroxidation and increase resistance to ferroptosis induction in triple-negative breast cancer, whereas ACSL4-driven polyunsaturated phospholipid remodelling enhances ferroptosis susceptibility." (PMID 42226605, 2026). "Increased ACSL4 expression is observed in tumors, particularly triple-negative breast cancer, where higher ACSL4 levels may enhance sensitivity to radiotherapy and chemotherapy." (PMID 40527896, 2025). "Herein, we showed that Polyphyllin III, which is a major saponin extracted from Paris polyphylla rhizomes, exerted its proliferation-inhibitory effect on MDA-MB-231 triple-negative breast cancer cells mainly through ACSL4-mediated lipid peroxidation elevation and ferroptosis induction." (PMID 34040532, 2021). "A high level of ACSL4 correlates with triple-negative breast cancers." (PMID 22808264, 2012). "Furthermore, increased expression of ACSL4 has been observed in various tumor tissues, particularly in triple-negative breast cancer, and tumor cells with elevated ACSL4 expression may exhibit greater sensitivity to radiotherapy and chemotherapy." (PMID 37893066, 2023). "However, the upstream regulatory mechanisms leading to differential ACSL4 expression between triple negative breast cancer and ERα-positive cells remained unknown." (PMID 31311992, 2019). "In triple-negative breast cancer (TNBC) cell lines, SP1 is an activator of acyl-CoA synthetase 4 (ACSL4), which catalyzes the conversion of fatty acids to their active acyl-CoA form." (PMID 36077352, 2022). "As an additional significant finding, a combination of rosiglitazone and 4-OHTAM was also effective in inhibiting cell proliferation and tumor growth in cells that do not express ER and overexpress ACSL4, such as the very aggressive triple negative breast cancer cell line MDA-MB-231." (PMID 26536660, 2015). "A meta-analysis of public gene expression databases indicated that ACSL4 expression is positively correlated with a unique subtype of triple negative breast cancer (TNBC), characterized by the absence of androgen receptor (AR) and therefore referred to as quadruple negative breast cancer (QNBC)." (PMID 24155918, 2013).
triple-negative breast carcinoma (continued). "The combination was effective in inhibiting cell proliferation and tumor growth in a very aggressive triple negative breast cancer cell line, MDA-MB-231, which does not express ER and overexpresses ACSL4." (PMID 26536660, 2015).
atherosclerosis (14 papers, 2020 to 2025). A disease characterized by the build-up of fatty material and calcium deposition in the arterial wall resulting in partial or complete occlusion of the arterial lumen. "Berberine has a protective role in preventing vascular endothelial cell damage and delaying the progression of atherosclerosis by reducing the stability of ACSL4 to counteract ferroptosis caused by lipid peroxidation." (PMID 40979213, 2025). "BBR has been identified as a novel ACSL4 inhibitor with the ability to inhibit endothelial ferroptosis and atherosclerosis." (PMID 39338381, 2024). "The expression of PTGS2 and ACSL4 in human coronary artery specimens is positively correlated with the severity of atherosclerosis." (PMID 39396974, 2024). "Lipid metabolism disorder is the basis of atherosclerosis, and although the link between ferroptosis and atherosclerosis is not fully understood, there is evidence of significant upregulation of ACSL4 protein in tissue samples from atherosclerosis patients." (PMID 37372148, 2023). "Inhibition of ACSL4 can improve atherosclerosis by inhibiting vascular endothelial ferroptosis." (PMID 39595632, 2024). "Furthermore, the severity of atherosclerosis was positively correlated with the expression of Ptgs2 and ACSL4 and negatively correlated with the expression of GPX4." (PMID 36192693, 2022). "Moreover, the positive correlation between the severity of atherosclerosis and ACSL4 also implied that ferroptosis regulated the occurrence and progression of atherosclerosis." (PMID 35096837, 2021). "Furthermore, rosiglitazone inhibits ACSL activity and fatty-acid partitioning in human and mouse arterial smooth muscle cells and human macrophages, suggesting that ACSL4 may regulate fatty-acid partitioning and the biological effects of atherosclerosis." (PMID 37372148, 2023). "For example, a study found that two ferroptosis-related proteins, PTGS2 and ACSL4, and two necroptosis-related proteins, NLRP3 and caspase-1, are upregulated in the advanced stages of atherosclerosis (AS) and are positively correlated with the severity of AS." (PMID 39072329, 2024).
ischemia (12 papers, 2019 to 2025). A hypoperfusion of the BLOOD through an organ or tissue caused by a PATHOLOGIC CONSTRICTION or obstruction of its BLOOD VESSELS, or an absence of BLOOD CIRCULATION. "One study found that ischemia-induced ACSL4 activation contributes to ferroptosis-mediated tissue injury in intestinal I/R." (PMID 35873574, 2022). "In the transient cerebral ischemia model, the expression of ACSL4 was suppressed at 1 h and 3 h after ischemia, while the ACSL4 level was significantly increased at 24 h after reoxygenation." (PMID 35855863, 2022). "Acyl-CoA synthetase long-chain family member 4 has been found to be upregulated after ischemia and involved in ischemia-reperfusion injury." (PMID 34149358, 2021). "After ROSI administration, ACSL4 was inhibited in the ischemia + ROSI group compared with in the ischemia group." (PMID 30737476, 2019). "Relative to the baseline, ACSL4 demonstrated an upward trend in both regions post‐ischemia." (PMID 40376919, 2025). "Therefore, this study thus shed new light on the pathological engagement of ACSL4-mediated ferroptosis in intestinal ischemia/reperfusion injury." (PMID 34733403, 2021). "In addition, the inhibition of ferroptosis can ameliorate in situ and remote organ injury, in detail, ACSL4 is induced after ischemia and is involved in ischemia/reperfusion injury in the intestine." (PMID 32103754, 2020). "In this study, we hypothesize that ferroptosis participates in intestinal I/R injury, and that the activation of ACSL4 during ischemia contributes to ferroptosis after reperfusion." (PMID 30737476, 2019). "Similarly, oral administration of rosiglitazone could inhibit ACSL4, suppress lipid peroxidation, and thus alleviate ischemia/reperfusion-related mucosal injury." (PMID 34733403, 2021). "In an intestinal ischemia–reperfusion mouse model, an elevated level of AARS2 mediated K18 lactylation of histone H3 on the acyl-CoA synthetase long-chain family member 4 (ACSL4) promoter, activating its expression and subsequent cell ferroptosis." (PMID 41008630, 2025). "Immunofluorescence detection results revealed differential expression patterns of GPX4 and ACSL4 in the peri‐infarct cortex and hippocampal CA1 region post‐ischemia." (PMID 40376919, 2025). "Indeed, the changes seen for several proteins related to this process (ACSL4, TFRS, GPX4, etc.), as well as the increase seen for the final product of lipid peroxidation, MDA, were indicative of ferroptosis up-regulation after 21 days of FAL induced ischemia." (PMID 39004727, 2024). "Then, we established an ischemia model in mice pretreated with or without ROSI, which could inhibit ACSL4 and prevent ferroptosis." (PMID 30737476, 2019).
colitis (11 papers, 2022 to 2026). Inflammation of the colon. "ACSL4 has been observed to be upregulated in the ileum and colon of patients diagnosed with CD and UC, as well as in mice with experimentally induced colitis using dextran sulfate sodium." (PMID 39247444, 2024). "The study demonstrated an increase in ACSL4 expression in an in vitro colitis model using LPS-stimulated Caco-2 cells and immune cells from individuals with UC." (PMID 39247444, 2024). "Here we show that the MALT1 protease inhibits Acsl4 expression during recovery from experimental colitis in mice." (PMID 37108564, 2023). "Moreover, the supplementation of HT significantly downregulated the increased ACSL4 in DSS-induced colitis while it upregulated the decreased Gpx4 both in mRNA and protein expression, suggesting that HT suppressed ferroptosis in colitis in vivo." (PMID 39064786, 2024). "ACSL4 was downregulated and Gpx4 was upregulated by HT treatment in colitis." (PMID 39064786, 2024). "Moreover, ERC-exos treatment further enhanced the levels of GSH and the expression of GPX4 but reduced the levels of iron, MDA, and expression of ACSL4 in the colon of colitis mice." (PMID 36045952, 2022). "Therefore, the increased levels of PBLD, FAM3D, KRT8, SULT2B1, GPA33, DEPTOR, and decreased expression of ACSL4, IFITM1 and HSD11B1 caused by mEVs has been demonstrated to attenuate colitis, implying that consumption of mEVs has the potential to improve intestinal health." (PMID 35893911, 2022). "In a DSS‐induced colitis mouse model, the DSS group showed higher expression of ACSL4 and lower expression of GPX4 and FTH1 compared to the WT group." (PMID 41098076, 2025). "In detail, HT downregulated ACSL4 and PTGS2 mRNA and protein, while it upregulated Gpx4 mRNA and protein, suggesting that HT suppressed ferroptosis in colitis in vitro." (PMID 39064786, 2024). "Consistent with the results from in vitro experiments, we observed a reduction in the expression of Gpx4, while Acsl4 and Alox5 were upregulated in the DSS‐induced colitis model at the transcription level." (PMID 38340032, 2024). "Meanwhile, no apparent difference was observed in ferroptosis-related proteins between 2 groups of mice after DSS treatment, including ACSL4, GPX4, and FTH1, suggesting that ferroptosis contributed minimally to the aggravated colitis in Gab1IEC-KO mice." (PMID 36795486, 2023). "Consistent with the advanced results, GPX4 expression and GSH synthesis were increased in the ERC-exos-treated group, while iron, MDA, and the expression of ACSL4 were decreased in the DSS-induced group, which suggested that ERC-exos can downregulated ferroptosis in colitis." (PMID 36045952, 2022). "Interestingly, IHC staining results revealed that, except for TXNRD1, the expression levels of ACSL4 and LPCAT3 in colitis mice were higher than those in the normal control group, while SLC7A11 and GPX4 displayed the opposite consequence." (PMID 40691131, 2025).
diabetic nephropathy (11 papers, 2021 to 2025). "Association of baseline tubular ACSL4 expression levels with risk for rapid progression of diabetic kidney disease in the study cohort." (PMID 40182632, 2025). "Correlations between tubular ACSL4 expression levels and clinical characteristics of patients with diabetic kidney disease." (PMID 40182632, 2025). "The glucose-lowering medication rosiglitazone inhibits ACSL4, thereby reducing lipid peroxidation and iron content in renal tubular cells, which helps mitigate diabetic nephropathy." (PMID 37746707, 2023). "In patients with diabetic nephropathy, the iron death-related factors ACSL4, PTGS2, and NOX1 were significantly increased, and GPX4 was significantly decreased." (PMID 34735495, 2021). "Recently, wang et.al found increased expression levels of ACSL4 in diabetic nephropathy mice, while ACSL4 inhibitor rosiglitazone could improve kidney function." (PMID 36503536, 2022). "Furthermore, ACSL4 inhibitors can block the iron death of renal tubular cells and inhibit the production of pro-inflammatory cytokines, which finally relieves the symptoms of diabetic nephropathy." (PMID 34735495, 2021). "The present study have found that serum ferroptosis markers GPX4 and ACSL4 as well as iron metabolism indexes are closely related to the severity of renal disease in type 2 diabetic patients, which may become biomarkers for diagnosis and treatment monitoring of diabetic nephropathy in the future." (PMID 38189040, 2023). "A recent study showed that diabetic mice had significantly increased levels of acyl-CoA synthetase long-chain family member 4 (ACSL4) and decreased GPx4, and those findings suggest that ferroptosis was involved in the pathogenesis of diabetic nephropathy." (PMID 33477607, 2021).
Obesity (11 papers, 2014 to 2025). Accumulation of substantial excess body fat. "In summary, ACSL4’s association with obesity is mainly manifested in its effect on fatty-acid metabolism." (PMID 37372148, 2023). "In early pregnancy, obesity leads to ovarian dysfunction, which is closely associated with ACSL4-mediated fatty-acid synthesis." (PMID 37372148, 2023). "Clinical biopsy results show a positive correlation between lipid peroxidation deposition and the expression of the ferroptosis core gene ACSL4 in the liver tissue of patients with obesity-related fatty liver disease." (PMID 40689204, 2025). "IR in obesity promotes lipolysis in adipose tissue, releasing free fatty acids (FFAs) that upregulate ACSL4 in hepatocytes, thereby enriching membranes with PUFAs susceptible to peroxidation." (PMID 40689204, 2025). "Further studies are needed to elucidate the interplay between these pathways regarding the inhibitory effect of hypoxia on ACSL4, especially in various AT depots and in the context of pathophysiological conditions such as obesity and aging." (PMID 40862726, 2025). "Obesity-driven hyperlipidemia elevates circulating PUFAs (e.g., AA), which are incorporated into hepatocyte membranes via ACSL4/LPCAT3." (PMID 40689204, 2025). "ACSL4 controls the occurrence and development of obesity mainly by regulating fatty-acid metabolism, mitochondrial function, and hormone secretion." (PMID 37372148, 2023). "Taken together, exploring the regulation of ACSL4 might hold promise to find novel avenues to combat obesity and to promote healthy aging as both conditions are tightly linked." (PMID 40862726, 2025). "In addition, a transcriptomic study of flaxseed polysaccharide (FP)-treated rats also suggests an important role for ACSL4 in the development of obesity." (PMID 37372148, 2023). "For example in an in vivo model, ACSL4 activity was shown to be important in regulating the incorporation of arachidonic acid into phospholipids as well as the downstream effects of diet‐induced obesity, including adipose tissue inflammation." (PMID 35510808, 2022). "In addition to limiting excessive calorie intake from exogenous sources, future modification of ACSL4 through gene-editing technology without affecting its normal function may be an effective way to treat obesity." (PMID 37372148, 2023).
colon adenocarcinoma (10 papers, 2010 to 2022). "Increased ACSL4 expression, both at mRNA and protein levels, in colon adenocarcinoma cells has been associated with inhibition of apoptosis and increase in cell proliferation when compared to adjacent normal tissue." (PMID 21085606, 2010). "Previous investigations in colon adenocarcinoma or hepatocellular cells reported that ACSL4 overexpression or inhibition associated only with increased or decreased cell proliferation respectively." (PMID 21085606, 2010). "Moreover, in colon adenocarcinoma where ACSL4 expression is associated with an increased proliferation rate, ACSL1 expression was not changed or was even down-regulated." (PMID 21085606, 2010). "For example, an increase in ACSL4 expression is related to the differentiation of colon adenocarcinoma." (PMID 35237519, 2022). "Various potential biomarkers for colon adenocarcinoma initiation and progression and drug targets were identified and discussed, including seven novel markers: ACSL4, ANK2, AMER3, EXOSC1, EXOSC6, GCLM, and TFRC." (PMID 35842572, 2022). "For example, previous reports suggest that the up-regulation of acyl-CoA synthetase long chain family member 4 (ACSL4) promotes tumor cell survival in human colon adenocarcinomas, and that fatty acid–binding proteins can channel lipids from surrounding tissues to fuel further tumor growth." (PMID 32817263, 2020). "Previous reports have indicated that other ACS isozymes, such as ACSL4 and ACSL5, are overexpressed in various types of cancer, including colon adenocarcinoma." (PMID 25749516, 2015).